NCKIPSD (NCK interacting protein with SH3 domain)
Description:
Has an important role in stress fiber formation induced by active diaphanous protein homolog 1 (DRF1). Induces microspike formation, in vivo (By similarity). In vitro, stimulates N-WASP-induced ARP2/3 complex activation in the absence of CDC42 (By similarity). May play an important role in the maintenance of sarcomeres and/or in the assembly of myofibrils into sarcomeres. Implicated in regulation of actin polymerization and cell adhesion. Plays a role in angiogenesis.
Synonyms: VIP54; WISH; AF3P21; SPIN90; ORF1; WASLBP; DIP1; DIP
Tractability: Small molecule: a structure with a bound ligand is known. Antibody: its Gene Ontology location is reachable by antibodies, with high confidence. PROTAC: ubiquitination databases record sites on it; its protein half-life has been measured.
Gene: Protein-coding gene on chromosome 3 (48,673,841 to 48,686,364, reverse strand). Ensembl gene ENSG00000213672.
Subcellular location: Nucleus
Subcellular location (Human Protein Atlas): Nucleoplasm; Plasma membrane
Pathways (Reactome):
Disease: FCGR3A-mediated phagocytosis
Immune System: Regulation of actin dynamics for phagocytic cup formation
Signal Transduction: RHO GTPases Activate WASPs and WAVEs
Gene Ontology:
Molecular function: protein binding; Arp2/3 complex binding; cytoskeletal protein binding
Biological process: cytoskeleton organization; endocytosis; positive regulation of neuron projection development; regulation of postsynapse assembly
Cellular component: COP9 signalosome; nucleoplasm; cytosol; intermediate filament; glutamatergic synapse; nucleus; postsynapse
Genetic constraint (gnomAD): Loss-of-function variants: 48 observed, 68.89 expected, observed/expected ratio (o/e) 0.7, 90% interval 0.55 to 0.89. The upper end of that interval is the gene's LOEUF score, 0.89, which puts it in group 3 of 6, group 1 being the genes least tolerant of losing a copy. Missense variants: 884 observed, 934.96 expected, observed/expected ratio (o/e) 0.95, 90% interval 0.89 to 1. Synonymous variants: 422 observed, 390.67 expected, observed/expected ratio (o/e) 1.08, 90% interval 1 to 1.17.
Homologues: Orthologues: chimpanzee NCKIPSD (99% identical), pig NCKIPSD (93% identical), dog NCKIPSD (93% identical), macaque NCKIPSD (90% identical), rat Nckipsd (89% identical), mouse Nckipsd (88% identical), guinea pig NCKIPSD (88% identical), tropical clawed frog nckipsd (64% identical), zebrafish nckipsd (56% identical), Drosophila melanogaster CG2258 (32% identical).
Diseases named in the same sentence as NCKIPSD in open-access papers:
NCKIPSD is named in the same sentence as 14 diseases in open-access papers, as found by Europe PMC text mining. Sharing a sentence is not in itself a finding about the gene and the disease. The quoted sentences say what the papers report.
breast carcinoma (5 papers, 2018 to 2024). "A very recent study reported that NCKIPSD downregulation and increased α-tubulin acetylation promotes stiffness of tumor stroma, which in turn, may inhibit chemotherapeutic drug uptake and regulate tumor sensitivity to chemotherapy, resulting in high risk of breast cancer recurrence within 5 years." (PMID 29915691, 2018). "Moreover, the downregulation of NCKIPSD, the promoter of which was observed to be hypermethylated among WTC survivors with breast cancer, has previously been shown to be associated with poor prognosis among breast cancer patients." (PMID 35564499, 2022).
colon cancer (3 papers, 2018 to 2023). "Consistently, our findings also showed decreased NCKIPSD expression is associated with high risk of colon cancer recurrence." (PMID 29915691, 2018). "Our results support a hypothesis that transgelin interacts with PARP1 and regulates the expression of downstream key genes (CALM1, MYO1F, NCKIPSD, PLK4, RAC1, WAS and WIPF1), which are mainly involved in the Rho signaling pathway in the human RKO colon cancer cells." (PMID 32774160, 2020).
Obesity (1 paper, 2025). Accumulation of substantial excess body fat. "Further, we investigated in more detail selected DMRs in TSC22D1, HAS2, GCC1, NCKIPSD from SAT, all being hypermethylated in individuals with obesity and BCCIP, IL1R1 (hypermethylated in lean) and FMNL2 (hypermethylated in individuals with obesity) from OVAT." (PMID 41225618, 2025).
cancer (2 papers, 2022 to 2023). A tumor composed of atypical neoplastic, often pleomorphic cells that invade other tissues. "Overall, these analyses recapitulate many of the already described markers of EMT transformation, and also suggest that ELL and NCKIPSD mutations may affect the cancer cell’s ability to undergo EMT transformation." (PMID 36774358, 2023).
NCKIPSD also shares sentences with these, for which no sentence is quoted: tumor (3 papers); breast tumor (2); depression (2); Anxiety (1); autism (1); brain disorder (1); Cognitive impairment (1); Crohn disease (1); neurological diseases (1); Parkinson disease (1).